RHEX (regulator of hemoglobinization and erythroid cell expansion)
Description:
Acts as a signaling transduction factor of the EPO-EPOR signaling pathway promoting erythroid cell differentiation.
Synonyms: C1orf186; FLJ16052
Tractability: Antibody: UniProt places it where antibodies can reach, with high confidence; its Gene Ontology location is reachable by antibodies, with high confidence; UniProt predicts a signal peptide or a membrane-spanning region; the Human Protein Atlas places it where antibodies can reach.
Gene: Protein-coding gene on chromosome 1 (206,053,173 to 206,102,449, forward strand). Ensembl gene ENSG00000263961.
Subcellular location: Cell membrane
Subcellular location (Human Protein Atlas): Plasma membrane
Gene Ontology:
Molecular function: erythropoietin receptor binding; protein binding
Biological process: cellular response to erythropoietin; erythropoietin-mediated signaling pathway; positive regulation of erythrocyte differentiation
Cellular component: plasma membrane
Genetic constraint (gnomAD): Loss-of-function variants: 17 observed, 16.46 expected, observed/expected ratio (o/e) 1.03, 90% interval 0.71 to 1.54. The upper end of that interval is the gene's LOEUF score, 1.54, which puts it in group 6 of 6, group 1 being the genes least tolerant of losing a copy. Missense variants: 178 observed, 210.29 expected, observed/expected ratio (o/e) 0.85, 90% interval 0.75 to 0.96. Synonymous variants: 83 observed, 77.31 expected, observed/expected ratio (o/e) 1.07, 90% interval 0.9 to 1.29.
Homologues: Orthologues: chimpanzee RHEX (99% identical), macaque RHEX (84% identical), pig RHEX (69% identical), dog RHEX (68% identical), guinea pig RHEX (54% identical).
Diseases named in the same sentence as RHEX in open-access papers:
RHEX is named in the same sentence as 3 diseases in open-access papers, as found by Europe PMC text mining. Sharing a sentence is not in itself a finding about the gene and the disease. The quoted sentences say what the papers report.
endometrial cancer (1 paper, 2025). Primary or metastatic malignant neoplasm involving the endometrium (mucous membrane that lines the endometrial cavity). "Additionally, another study identified a a panel of fivegenes (ASRGL1, RHEX, SCGB2A1, SOX17, and STX18) as biomarkers for predicting lymph node metastasis in early-stage endometrial cancer patients." (PMID 39980551, 2025).
RHEX also shares sentences with these, for which no sentence is quoted: monoclonal gammopathy (1 paper); ovarian carcinoma (1).